IFNG (interferon gamma)
Diseases named in the same sentence as IFNG in open-access papers (continued):
Sharing a sentence is not in itself a finding about the gene and the disease.
Autoimmunity (343 papers, 2006 to 2026). The occurrence of an immune reaction against the organism's own cells or tissues. "Older mice with TIM1 mutation showed decreased IL-10 secretion from B cells, spontaneous autoimmunity associated with T cell overactivity, increased IFNγ production, and elevated serum Ig and autoantibody levels." (PMID 40075055, 2025). "Several studies have revealed that miR-183C miRNAs are critically involved in immunity and autoimmunity via regulating T cell activation, inflammatory cytokine IFNγ production, Tregs, and pathogenic Th17 cells differentiation and function." (PMID 35873462, 2022). "T1 and T17 polarization are associated with autoimmunity and production of the cytokines IFNγ and IL-17 respectively." (PMID 35860254, 2022). "IFNγ has also been implicated in early autoimmunity as its levels are elevated concurrently with autoantibody production in ANA+ healthy individuals." (PMID 33519824, 2020). "Since autoimmunity in IFNγ−/− mice is characterized by deficiency of the encephalitogenic Th1 repertoire and is predominantly Th17-cell driven, the role of Th17-cells is hence further substantiated." (PMID 30429853, 2018). "The role of DN T cell-secreted IFNγ in Fas- and FasL-deficient autoimmune lymphoproliferative states is unclear, and requires further investigation." (PMID 23077665, 2012). "Loss of IFNg producing cells and suppression of Th1 autoimmunity." (PMID 34447383, 2021). "IFNγ drives both dramatic changes in chromatin accessibility and the production of pathogenic autoantibodies, highlighting the potential importance of epigenetic control of autoimmunity." (PMID 33519824, 2020). "The past few years have been particularly fruitful in three domains: the role of PI3K signaling in loss of B cell tolerance, the role of IFNγ signaling in the development of autoimmunity, and the characterization of changes in chromatin accessibility in SLE B cells." (PMID 33519824, 2020). "At the later stage of Th1 cell differentiation, T-bet–BCL6complex represses Ifnγ transcription to keep the production of IFN-γin control as excessive production of IFN-γ could cause autoimmunity." (PMID 25123277, 2014). "Possibly, IFNγ-induced NO production in FRC or other host cells participates in the active down-regulation of T cell responses to limit tissue damage associated with acute inflammation or autoimmunity." (PMID 22973278, 2012). "It was suggested that increased IL-12 and IFNγ may indicate stimulation of Th1 cells pathogenetically linked to autoimmunity in autism." (PMID 22748016, 2012). "This is similar to mercury-induced autoimmunity, in which the key factor was identified as IFNg instead of IFNa." (PMID 41155532, 2025). "Pro-inflammatory T helper cell subsets, such as Th1 and Th17 cells, contribute to autoimmunity by producing potent cytokines like Interferon gamma (IFN-γ) and IL-17, respectively, which amplify local inflammation and tissue damage." (PMID 41322400, 2025). "Interferon-gamma (IFN-γ) holds significant interest in the field of autoimmunity research due to its influential role in promoting and regulating inflammation." (PMID 39877346, 2024). "This trend was also visualized with IP-10, a chemokine downstream of interferon gamma (IFN-γ), and TNF-α, a cytokine implicated in chronic inflammation and autoimmunity and also associated with PCCs." (PMID 38312212, 2024). "In heart recipients with coronary artery vasculopathy, T cells tend to produce less IL-10 and more IL-17 and IFNγ, indicating a Th17 response that promotes autoimmunity." (PMID 39408890, 2024). "Our previous work identified a beneficial role for IFNγ signaling in astrocytes during chronic CNS autoimmunity." (PMID 37828609, 2023). "Treg cluster 6.4 was inverse correlated with IFNg production in response to PPI as expected if this Treg subset suppresses autoimmunity." (PMID 36505460, 2022).
Autoimmunity (continued). "Expression of the IFN-sensitive genes regulates the impact of IFNγ in pro-inflammatory effector functions, and in anti-TGFβ fibrotic processes that maintain autoimmunity." (PMID 36425763, 2022). "Inhibition of anabolic adaptation, which fuels IFNγ production, constitutes a promising approach toward mitigating the effects of IFNγ in autoimmunity." (PMID 36425763, 2022). "Global ablation of IFNγ rescues the Treg cell defect and autoimmunity in Foxp3CremiR-142fl/fl mice, thus providing further evidence for the essential role of the miR-142-IFNγ signaling pathway in the regulation of Treg cell homeostasis and function." (PMID 35180231, 2022). "The roles of IFNγ and IL-10, expressed respectively by B effector 1 (Be1) and Bregs, have been established in pathogen clearance, tumor growth, autoimmunity and allograft rejection." (PMID 35359977, 2022). "Several factors that play important roles in autoimmunity are present in TA and CD, such as lymphocyte subtype and proinflammatory cytokines (IFNγ, TNFα, IL-6, IL-17, IL-18)." (PMID 33628228, 2021). "Taken together, our data reveal a protective role for IFNγ in chronic neuroinflammation and identify a novel function of the iP in astrocytes during CNS autoimmunity." (PMID 32532298, 2020). "B cell intrinsic defects that induce autoimmunity such as WAS-deficiency, constitutive activation of Btk, or galectin-3 deficiency can drive IFNγ production by T cells in a manner dependent on B/T interaction." (PMID 33519824, 2020). "IFNγ has long been known to promote autoimmunity and nephritis in several murine lupus models, including NZB x NZW F1 mice, MRL.lpr mice, and pristane treated mice." (PMID 33519824, 2020). "Infiltrating CD4+ T cells were found as the source of this IFNγ,3 and the adoptive transfer of IFNγ‐producing T‐cell lines has been demonstrated to promote autoimmune pathologies." (PMID 33135395, 2020). "Here, we demonstrate that IFNγ signaling in regional astrocytes induces the iP and promotes protection of the CNS during chronic autoimmunity." (PMID 32532298, 2020). "Consistent with this notion we have demonstrated the essential role of B cell intrinsic IFNγ signaling in autoreactive B cell development in TLR7-promoted SLE-autoimmunity." (PMID 32849556, 2020). "Taken together, these observations suggest that IFNγ signaling in B cells contributes to autoimmunity by promoting the development of spontaneous GCs as well as supporting the development and subsequent differentiation of ABCs and DN2 cells." (PMID 33519824, 2020). "Considering the evident importance of IFNγ in autoimmunity, neutralization, or reduction of IFNγ has been tried as a therapeutic modality in mice and human SLE." (PMID 31354738, 2019). "Although elevated levels of IFNγ can, under certain conditions, drive the development of autoimmunity, sterile IFN signaling can suppress follicle and germinal center formation." (PMID 31126966, 2019). "We then assessed the development of autoimmunity in IFNγ−/− mice since these mice are defective in Th1 responses." (PMID 30429853, 2018). "Together, the commonality of these models is the prominent role of IFNγ in generating autoreactive responses, and the parallel pathways B and T cells can take (depending on the model) to generate autoimmunity." (PMID 29568300, 2018). "Tc17 effectors also potentiate autoimmune actions of Th17 cells during EAE and exacerbate other autoimmune disorders due to their ability to express multiple cytokines e.g. IL-22, GM-CSF, M-CSF, IFNγ and IL-3." (PMID 28542595, 2017). "In many studies involving infection, tumor, and autoimmunity, Th17 cells are either short-lived or convert into IFNγ producing cells." (PMID 28542595, 2017). "Consistent with the finding that IL-12 is an important driver of Blimp-1-dependent Tr1 cell differentiation in autoimmunity, we found that Blimp-1 and IL-10 expression by IFNγ-producing CD4+ T cells from L. donovani-infected mice required IL-12." (PMID 26765224, 2016).
Autoimmunity (continued). "T and NK cells from Socs1 knockout mice produce more IFNγ and show resistance to Th17 dependent autoimmunity due to reduced Th17 cell differentiation." (PMID 26203907, 2015). "In activated T cells, CXCR3 expression is also important for the amplification of IFNγ-mediated recruitment into peripheral sites during infection and in autoimmunity." (PMID 24586509, 2014). "Deletion of another component of the miRNA machinery, drosha, specifically in Foxp3-expressing cells resulted in autoimmunity and overexpression of IFNγ and IL-4." (PMID 23345540, 2013). "Beside anti-microbial and inflammatory responses, IFNγ alsointerferes with growth suppression, cell death, tumor immunity and autoimmunity." (PMID 23445205, 2013). "Deletion of IFNγ in MRL.lpr mice resulted in reduced autoimmunity, lymphoproliferation and mortality." (PMID 23077665, 2012). "As a pro-inflammatory cytokine, IL-27 activates T helper 1 (TH1) responses in the early phases of immunity, in which secretion of interferon-gamma (IFN-γ) is one of the key inflammatory mediators in autoimmunity." (PMID 22827855, 2012). "The formation of IFNγ and IL-17–secreting autoreactive T cells has been demonstrated to be a prerequisite for the development of autoimmunity." (PMID 19468301, 2009). "Furthermore, NK cells are a major producer of IFNγ and are activated by Type I IFNs, linking their relevance in autoimmunity to our observed findings of increased IFN after JAKinib withdrawal." (PMID 40522928, 2025). "Furthermore, NK cells are a major producer of IFNγ and are activated by Type I IFNs, linking their relevance in autoimmunity to our observed findings." (PMID 39386576, 2025). "Taken together, these results suggest that pharmacological activation of LRH‐1/NR5A2 mitigates PBMCs‐induced β‐cells apoptosis likely via decreased CD8+ cytotoxic T‐cells and reduced IFNγ, a key cytokine contributing to the triggering and amplification of autoimmunity." (PMID 39702941, 2024). "SOCS3 was found to inhibit the production of IL-1 and IFNγ in vitro, implying that it may influence autoimmunity in T1D." (PMID 37400916, 2023). "FOXD1 is involved in autoimmunity through its regulation of IFNγ, IL2, IL4, and NFAT complexes." (PMID 35328504, 2022). "Cells within the CD4_Stim2.Th17.1 cluster expressed genes associated with regulatory function (IL10, ITGA2), whereas cells within the CD4_Stim2.Th17.2 cluster expressed proinflammatory effectors (IFNG, IL23R, PRF1), described to be produced by pathogenic Th17 cells in autoimmunity." (PMID 35192548, 2022). "Pharmacological interventions that selectively target the molecular interactions of survivin could be an attractive approach to improve control of IFNγ-dependent autoimmunity and treatment of RA." (PMID 36425763, 2022). "These previous data were, however, mainly acquired in the context of autoimmunity, where B cells receive a multitude of different signals and IFNγ signaling seems primarily to synergize with BCR-, CD40- and TLR-mediated stimuli to induce spontaneous germinal centers." (PMID 35187121, 2022). "The flexibility of Treg and Th17 cell differentiation provides us with a model system where the plasticity and unstable phenotypes of Tregs, Th1, Th17, and Th17 + IFNγ + cells will have important biological implications for designing therapeutic regimens to control autoimmunity." (PMID 34881246, 2021). "Interestingly, meningeal B cells exhibited a strong plasma cell response (Xbp1high), and a pro-inflammatory activation state characterized by expression of genes related to CNS inflammation and autoimmunity, including Il6, Ifnγ, Ifnγr, Il23, and Tnfα." (PMID 33277355, 2021). "Although we and others showed a crucial role for STAT1 in IFNγ signaling and autoimmunity, we found STAT4 to be dispensable in the formation of spontaneous GCs, T cell activation, complement deposition in the kidney, or the generation of T helper 1 cells in various autoimmune- and SLE-prone mice." (PMID 34638804, 2021).
Autoimmunity (continued). "A role for interferon gamma (IFNγ) has been proposed for both allergy and autoimmunity." (PMID 33584703, 2020). "In mouse models and in humans, T cells nonresponsive to IL-10 escape Treg control, proliferate to a greater degree, and produce higher amounts of inflammatory cytokines such as Th17 and IFNγ, both of which activate macrophages and promote cellular autoimmunity." (PMID 32303238, 2020). "Additionally, Tfh mediated autoimmunity in Roquinsan/san mice was induced by the accumulation of excessive IFNγ producing T cells due to delayed degradation of IFNγ mRNA." (PMID 31354738, 2019). "Prior studies demonstrated that type II IFN (i.e., IFNγ) played a requisite role in salivary gland autoimmunity in NOD mice but the lack of type II IFN signaling (either in IFNγ-deficient or IFNγ receptor-deficient NOD mice) did not abrogate dacryoadenitis." (PMID 30347820, 2018). "Thus, further characterization of the synergy between IFNγ and Gal-9 during the induction of Ido1 and Ido2 is important to our understanding the pathophysiology of autoimmune disorders such as MS, Hashimoto’s disease, or rheumatoid arthritis." (PMID 27799931, 2016). "Suppressive effects of iNKT cells in autoimmunity are generally thought to be caused by production of the Th2 cytokines IL4 and IL-13, while their immunostimulatory effects in other tumor systems are typically IFNγ-dependent." (PMID 22880059, 2012). "Diminished cytokine secretion in exhausted T-cells, may lead to reduced levels of the pro-inflammatory cytokines IL2 and IFNγ, possibly resulting in impaired functioning and activation of autoimmunity by continuous antigen stimulation to the T-cell receptor (TCR)." (PMID 35328504, 2022). "However, Hif1a haploinsufficiency had little impact on the dysregulated IFNγ production in miR-142–deficient Treg cells and failed to prevent development of fatal autoimmunity in Foxp3CremiR-142fl/fl mice." (PMID 35180231, 2022). "In this sense, the objective of the present study was to identify polymorphisms in important mediators of the immune response (FOXP3, IFNG, IL6, IL8, IL10, MBL2, CRP, TGFΒ1 and TNFA) in association with ANAs, which could contribute to the development of autoimmunity in hepatitis C." (PMID 32743104, 2020). "Furthermore, B cell-derived IL-6 synergized with IFNγ to mediate autoimmunity." (PMID 29568300, 2018). "Moreover, the propensity of Tregs from patients with autoimmunity to produce inflammatory cytokines could be ablated by using CRISPR to remove genes for IFNγ or IL-17 from engineered Treg." (PMID 29176976, 2017). "IL-10 is capable of inhibiting the synthesis of proinflammatory cytokines, while IL-12 is linked to autoimmunity by stimulating the production of interferon-gamma (IFN-γ) and tumor necrosis factor-alpha (TNF-α) from T and natural killer (NK) cells, and by reducing IL-4-mediated suppression of IFN-γ." (PMID 20379374, 2010). "IFNγ is one of the major cytokines produced by CD8 T cells in the context of infection, tumor control, and autoimmunity." (PMID 39231385, 2024). "The Th1 cell family including Th1 cells, transcription factor T-bet, and related cytokines IFNγ, TNFα, IL-2, IL-18, TGF-β, and IL-12 have been widely discussed in autoimmunity, such as SLE." (PMID 38164134, 2023). "Th1 cells and related transcription factor T-bet and inflammatory cytokines including IFNγ, TNFα, IL-2, IL-18, TGF-β, and IL-12 are important in inflammatory responses such as autoimmunity development." (PMID 38164134, 2023). "Compared with APP+/+ mESC-TEP-transplanted mice, the percentage of IFNγ-producing CD4 T cells in APP−/− mESC-TEP-transplanted mice showed a larger increase, which is probably due to enhanced anti-Aβ autoimmunity in APP−/− mESC-TEP-transplanted AD mice." (PMID 32849642, 2020).
Autoimmunity (continued). "Interferon alpha also shifts the immune response to a type 1 helper (Th1)-mediated pattern, resulting in the production of potent pro-inflammatory cytokines including interferon gamma (IFN-γ) and interleukin-2 (IL-2), thereby stimulating autoimmunity." (PMID 27632981, 2016). "Intriguingly, we found that BaP exposure of MRL mice results in the upregulation of serum IFNg but not IFNa1/a2, which is similar to the reported scenario of mercury-induced autoimmunity." (PMID 41155532, 2025). "The findings confirm a central role for interferon-gamma (IFN-γ) in vitiligo pathogenesis, although recent meta-analyses suggest that IFN-γ gene polymorphisms are more broadly associated with autoimmunity rather than being vitiligo-specific." (PMID 40430113, 2025). "By reducing IFNγ levels, BL001 helps restore immune homeostasis and mitigate autoimmunity." (PMID 39702941, 2024). "However, there is poor understanding of the contribution of immune activation to upstream signals that affect embryo implantation in systemic elevated interferon-gamma (IFN-γ) signaling, which occurs in autoimmunity and chronic inflammatory diseases." (PMID 38698852, 2024). "Th1 cells, generating interleukin (IL)-2, interferon-gamma (IFN-γ), and tumor necrosis factor-alpha (TNF-α), mainly take part in delayed-type hypersensitivity reactions and cell-mediated immune responses, such as autoimmune disorders." (PMID 35935951, 2022). "Trisomy 21 autoimmunity and HLH are both thought to be driven by interferon gamma." (PMID 36401314, 2022). "In contrast to PTPN22, PD-1 controlled proliferation but had no impact on IFNγ production indicating that negative regulation by PD-1 differs from PTPN22 and that not all co-factors have equal ability to cause autoimmunity." (PMID 32047502, 2020). "Gain of IFNγ production and reduction in IL-10 production by CD8 Tregs in PE IL-2Rα-KO mice may allow earlier advancement of autoimmunity." (PMID 33319815, 2020). "Although B cells expressing the IFNγR or the IFNγ-inducible transcription factor T-bet promote autoimmunity in Systemic Lupus Erythematosus (SLE)-prone mouse models, the role for IFNγ signaling in human antibody responses is unknown." (PMID 31090539, 2019). "Interferon gamma (IFNG) is a proinflammatory cytokine that is produced by various immune cells, including natural killer and CD4+ T helper 1 (Th1) cells, and plays an central role in the development of autoimmunity." (PMID 31752878, 2019). "For a number of years, IL-12-induced Th1 cells were thought to be the main drivers of autoimmunity, based on the findings that IFNγ-secreting CD4 T cells were frequently found at the site of inflammation and treatment with IFNγ led to exacerbated disease in multiple sclerosis patients." (PMID 27006754, 2015). "Collectively, these studies indicate that during lymphopenia, Foxp3 deletion or autoimmunity, a fraction of TREG cells could acquire a pro-inflammatory IFNγ-secreting phenotype." (PMID 23345540, 2013). "Further, owing the fact that autoimmunity is already mild or absent in this strain background, an effect of IFNγ deletion on this aspect of the lpr phenotype would be difficult to detect." (PMID 23077665, 2012). "It has been proposed that ongoing autoimmunity in the EAE mouse model is likely to represent the defective function of Tregs and lose FOXP3 expression under inflammatory conditions and can be induced to express proinflammatory cytokines, such as IL-17 and IFNγ (IFNγ+ FOXP3+ IL-17A+) (52, –, 54)." (PMID 37615438, 2023). "Interestingly, while mice with MALT1-deficient Tregs and mice with enzymatically-dead MALT1 in Tregs both developed autoimmune-like wasting disease, only full MALT1-KO in Tregs reduced splenic Treg frequencies and increased IFNg/IL17 production in conventional CD4 T cells." (PMID 32870913, 2020). "It is thus not surprising that IFNG- induced IDO-1 has also been shown to drive autoimmunity." (PMID 25928531, 2014).